TF (transferrin)
Diseases named in the same sentence as TF in open-access papers (continued):
Sharing a sentence is not in itself a finding about the gene and the disease.
lung carcinoma (continued). "We found increased levels of CRP, SAA, α-1-antitrypsin (AAT) by two distinct antibodies, and MUC1, and decreased levels of transferrin and gelsolin, in lung cancer sera." (PMID 16117833, 2005). "In cancer, lncRNA can act as oncogenes or tumor suppressors, where lncRNA promoters and/or their gene bodies can regulate TF expression, as seen in cncTRNs of gut and lung cancer, where lncRNAs are part of a network of inflammatory and tumoral diseases as key regulators of TFs." (PMID 41440381, 2025). "The TF-protein NANOG is reported as a prognostic biomarker for lung cancer." (PMID 39024368, 2024). "Additionally, transferrin-coated nanostructured lipid carriers loaded with plasmid DNA (Tf-NLC/pEGFP) were developed to enhance targeted gene delivery to lung cancer cells." (PMID 38794306, 2024). "Among them, the TF-protein MYC has been demonstrated as a therapeutic target for lung cancer." (PMID 39024368, 2024). "The results indicated enhanced tumor growth inhibition and selective cytotoxicity towards lung carcinoma cells, demonstrating the potential of transferrin-conjugated carriers in improving the delivery and efficacy of chemotherapeutic agents in lung cancer treatment." (PMID 38794306, 2024). "A progression from COPD to lung cancer was also indicated for TF and for APOA1." (PMID 35512017, 2022). "Transferrin receptor protein 1 (TFR1) is highly expressed in 88% of NSCLCs, which suggests that lung cancer cells could increase iron intake by enhancing the effects of the transferrin protein (TF) and TFR." (PMID 34616505, 2021). "If CBSF was modified by ligands that specifically identify lung cancer cells (e.g., transferrin, transformation factor α, hyaluronic acid, folic acid, and peptides) and used to package pDNA, the complex is expected to further inhibit the proliferation of cancer cells." (PMID 34685354, 2021). "The polymorphisms in HFE, TFR1 and TF (rs1799945, rs3817672 and rs1049296, respectively) did not appear to be correlated with lung cancer in our study." (PMID 30640897, 2019). "It has been demonstrated that high TF expression could be found in many different tumor cells, such as pancreatic carcinoma, lung carcinoma, and colorectal carcinoma, as well as in vascular endothelial cell and interstitial macrophages of tumor tissues." (PMID 28881799, 2017). "However, there is limited literature pertaining to the development of TfR-targeted drug/gene delivery systems for lung cancer, probably because of high endogenous transferrin concentrations in plasma and high TfR expression in the blood-brain barrier." (PMID 28290155, 2017). "It was concluded that TF-LP may be an efficient targeted drug-delivery system for lung cancer therapy." (PMID 25663858, 2015). "Recently, using 2D-DIGE, we identified several proteoforms of blood plasma proteins from lung cancer patients, including proapolipoprotein, apolipoprotein AIV, clusterin, gelsolin, fibrinogen, haptoglobin, hemopexin, transferrin, and serotransferrin." (PMID 35512017, 2022). "We investigated the concentrations of SF, hemoglobin (Hb) and transferrin (TRF) in 569 male primary lung cancer patients and 252 female primary lung cancer patients." (PMID 29190945, 2017). "A typical example showed that transferrin-decorated, lipid-based nanostructured material (NLC) loaded with PTX and plasmid DNA was used to treat NCI-H460 human lung cancer cells." (PMID 28290155, 2017). "This shows the first study in which silence of TF expression in lung adenocarcinoma cells by TF-siRNA could inhibit tumor growth and metastasis in vitro and in vivo, and the antitumor effects may be associated with inhibition of Erk MAPK, PI3K/Akt signal pathways in lung cancer." (PMID 21619686, 2011). "Similarly, a meta-analysis of case-control studies showed significantly higher levels of serum ferritin and TSAT among lung cancer cases (SMD=0.235 and SMD=0.07, respectively), but significantly lower levels of serum transferrin concentrations (SMD=-0.591)." (PMID 39246326, 2024).
lung carcinoma (continued). "Building on this approach, transferrin-modified solid lipid nanoparticles co-encapsulated with doxorubicin and plasmid DNA (T-SLN/DE) were formulated to facilitate both gene and drug co-delivery to lung cancer cells." (PMID 38794306, 2024). "Delving deeper into multifunctional carriers, transferrin-decorated nanostructured lipid carriers were designed to co-encapsulate paclitaxel and DNA (Tf-PTX-DNA-NLC), aiming for dual drug and gene delivery to lung cancer cells." (PMID 38794306, 2024). "The uptake of transferrin-decorated quantum dot nanoparticles was observed in A549 lung cancer and SH-SY5Y neuroblastoma cells but not in non-cancerous 16HB14o- or retinoic acid dopaminergic neurons differentiated SH-SY5Y cells." (PMID 37376099, 2023). "Analysis of correlation of iron level and iron metabolism parameters with tumour stage among lung cancer patients revealed a significant positive relationship for ferritin and a negative correlation for transferrin saturation." (PMID 30640897, 2019).
ovarian carcinoma (40 papers, 2001 to 2025). A malignant neoplasm originating from the surface ovarian epithelium. "The subsequent multivariate index assay is OVA1, which combines serum biomarkers CA125, transthyretin, transferrin, beta-2 microglobulin, and apolipoprotein A-1 to calculate a risk score for ovarian cancer." (PMID 38275400, 2024). "Transferrin has a great potential in assessing the risk of both ovarian cancer and functional iron deficiency in patients diagnosed with ovarian cancer." (PMID 36555993, 2022). "OVA1 is an FDA-approved blood test that measures the levels of five proteins (CA125, transferrin, transthyretin, apolipoprotein A1, and beta-2 microglobulin) to detect ovarian cancer risk in women." (PMID 36232415, 2022). "LncRNA associated with TF efficacy can serve as the prognostic and therapeutic biomarkers in ovarian cancer." (PMID 33949761, 2021). "Non-transferrin bound iron mediates cell death in ovarian cancer cells by inducing mitochondrial damage and loss of OMM proteins." (PMID 25697096, 2015). "While TF alone may have limited diagnostic value, its effectiveness improves when combined with other markers such as CA‐125, apolipoprotein A‐I, and transthyretin for early ovarian cancer detection." (PMID 40927964, 2025). "Combining transthyretin (TTR) with CA125, hemoglobin, apolipoprotein AI, and transferrin improved the detection of early-stage ovarian cancer compared to CA125." (PMID 38275400, 2024). "Among the challenges ahead and future studies are the identification of the entire landscape of TF gene profiles for early predictors of ovarian cancer and as effective targets for therapy." (PMID 38275417, 2024). "Transferrin-modified PEG-phosphatidyl-ethanolamine NPs that were specifically designed to target ovarian carcinoma cells expressing transferrin showed similar success." (PMID 37629007, 2023). "Mice injected with TF-overexpressing ovarian cancer cells exhibited enhanced venous thrombus formation following experimental stenosis, while mice bearing tumors under-expressing TF exhibited halted coagulation, platelet aggregation, and thrombus formation." (PMID 36013171, 2022). "The aim of the study was to evaluate the role of transferrin (Tf) as a marker of cancer of the ovary (CrO) and related FID." (PMID 36555993, 2022). "It was found that the use of the biomarker transferrin as a detection tool for ovarian cancer has only low sensitivity and specificity, at 72.9% and 74.1%, respectively." (PMID 33800113, 2021). "Nevertheless, periodic, recurring exposure to higher levels of transferrin can promote cancer development, including poorly-differentiated ovarian cancer." (PMID 34205023, 2021). "In another case-control study, the level of transferrin was measured using an immunological turbidimetric assay in the sera of 37 women with ovarian cancer and compared to those with benign ovarian diseases (N = 31) and age–matched healthy controls (N = 31)." (PMID 33800113, 2021). "The TF antigen is clearly expressed in most ovarian carcinomas, with minimal expression in benign and normal ovarian tissues." (PMID 32486344, 2020). "Consistently, plasma apoA-I levels were included in a FDA-approved test for early stage ovarian cancer, together with transthyretin, transferrin, β2-microglobulin and CA12540." (PMID 29396407, 2018). "Despite many observations of TF expression in several types of cancers, the association of tumour TF expression with risk of VTE has only been observed in pancreatic and ovarian cancer." (PMID 30314362, 2018). "The second test approved by the FDA, OVA1TM Ovarian Triage Test, combines a panel of five biomarkers for ovarian cancer (CA-125, transthyretin, apolipoprotein A1, ß2-microglobulin, and transferrin) identified through serum proteomics using SELDI-TOF-MS." (PMID 28837575, 2017). "More strikingly, the sensitivity in distinguishing normal versus mucinous early stage ovarian cancer, utilizing apoA-1, TF and TTR (CA125 excluded), was 95% (specificity 86%; AUC 95%)." (PMID 19662218, 2007).
ovarian carcinoma (continued). "Studies suggest altered transferrin levels in ovarian cancer." (PMID 40927964, 2025). "In addition, the combination of TTR and APOA1 with MUC16 and TF has shown a 96% overall sensitivity for early detection of ovarian cancer." (PMID 40836974, 2024). "However, in ovarian cancer the clear cell histology increases hypercoagulability, whereas the epithelial ovarian cancer increases VTE risk by increasing TF expression." (PMID 34064390, 2021). "In 2009, the Food and Drug Administration approved the clinical use of OVA-1, a serum test analyzing five biomarkers: CA-125, II-microglobulin (both elevated in ovarian cancer), apolipoprotein A1, prealbumin (transthyretin), and transferrin (which are decreased in ovarian cancer)." (PMID 28448435, 2017). "Moreover, transferrin pretreatment of ovarian cancer cells increases the intracellular iron level and enhances the sensitivity of the cells to ART, suggesting that iron has an important role in ART‐regulated cell death in ovarian cancer." (PMID 27860262, 2017). "Finally, our data also suggest that apoA-I, TTR, and TF, when analyzed collectively, are unique to ovarian cancer and thus provide for the first time a disease-specific multiple marker panel for the early detection of OC." (PMID 19662218, 2007). "TF has been previously reported to be decreased in serum of patients with ovarian cancer." (PMID 19662218, 2007). "It shows promising potential as a biomarker for early detection of ovarian cancer—especially when used alongside TTR and TF." (PMID 40927964, 2025). "The combination of CA125, transferrin, TTR and ApoA1, using a proteomic analysis, yielded a sensitivity of 89% at a specificity of 92% for the early detection of ovarian cancer." (PMID 33800113, 2021). "In ovarian cancer, mucins MUC1, MUC5AC, MUC6 and MUC16 are carriers of TF antigen; among them, MUC1 is a natural ligand for Gal-3." (PMID 32486344, 2020). "Three serum biomarkers, ApolipoproteinA-I, Transthyretin and Transferrin, combine with CA125 can be used to significantly improve detection of early stage ovarian cancer over CA125 alone." (PMID 19662218, 2007). "Among more than fifteen ovarian cancer‐related biomarkers identified to date, the most widely studied include CA‐125, HE4, kallikreins, prostasin (PSN), transthyretin (TTR), transferrin, vascular endothelial growth factor (VEGF), apolipoprotein A‐I (ApoA‐I), and osteopontin (OPN)." (PMID 40927964, 2025). "In addition, carbohydrate vaccines, including a pentavalent vaccine (Globo-H-GM2-sTn-TF-Tn) and a heptavalent vaccine (GM2-Globo-H-Lewis Y-Tn-sTn-TF-Tn-MUC1), have successfully elicited IgG and/or IgM responses in ovarian cancer patients." (PMID 39349440, 2024). "Moreover, relative carbohydrate vaccines (a pentavalent vaccine, Globo-H–GM2–sTn–TF–Tn, and a heptavalent vaccine, GM2–Globo-H–Lewis Y–Tn–sTn–TF–Tn-MUC1) are reported to elicit IgG and/or IgM responses in ovarian cancer patients." (PMID 36497322, 2022). "Notably, OVA1® is a United States (US) Food and Drug Administration (FDA) approved test, which includes apolipoprotein A-I (APOA1), transthyretin (TTR), transferrin (TF), β2-microglobulin (B2M), along with MUC16, and has demonstrated effectiveness in detecting early-stage ovarian cancer." (PMID 40836974, 2024). "In conclusion, we have shown that ApoA-I, TF, and TTR, in combination with CA125 in a multivariate predictive model, have the potential to improve the specificity and sensitivity for the early detection of ovarian cancer over CA125 alone, particularly for the mucinous histopathologic subtype." (PMID 19662218, 2007). "Most of them and their non-modified analogues like TF and Tn are well-described TACA, and some (e.g. SiaLea, SiaLex, SiaTn, GD3) have been shown to be overexpressed in ovarian cancer." (PMID 27764122, 2016).
ovarian carcinoma (continued). "Our finding that 6-OSulfo-TF but not its non-sulfated analogue TF, was (apart from CA125) the second-best HGSOC from control discriminator is noteworthy, because the role of glycan sulfation (in contrast to glycan sialylation) has not yet been studied in ovarian cancer." (PMID 27764122, 2016).
melanoma (39 papers, 2010 to 2025). A malignant, usually aggressive tumor composed of atypical, neoplastic melanocytes. "MELTF (also known as CD228) is a membrane-bound transferrin, first associated with melanoma development." (PMID 38168272, 2023). "Here we showed for the first time that the receptor is expressed on a panel of melanoma associated fibroblasts while to a lower extent on normal fibroblasts such as TF." (PMID 23049949, 2012). "In mouse models of melanoma and lymphoma, transferrin overexpression exacerbates liver metastasis, while its knockdown, antibody, designed peptides, and CD mutation interfering with transferrin–TCRα interaction inhibit metastasis." (PMID 39810853, 2025). "Altogether, these observations demonstrate that specific glycan patterns on tumor cells correlate with clinical outcome of melanoma patients, especially GlcNAc, NeuAc, TF-antigen and Fuc motifs being associated with poor outcome, whereas Man and Glc residues elicit better survival." (PMID 36891308, 2023). "The effects of transferrin on the melanoma model were evaluated by weight of the tumors metastasized to the liver." (PMID 39810853, 2025). "In summary, transferrin emerges as a promising targeting ligand when conjugated with NLCs for encapsulating Artemisone against melanoma, aligning with the mechanism of action typical of artemisinins." (PMID 39201805, 2024). "This study aimed to develop NLCs and transferrin-conjugated NLCs encapsulating Artemisone to facilitate its delivery and improve its anticancer activity against melanoma." (PMID 39201805, 2024). "As reported, the lipogenesis regulator SREBP2 directly induces transcription of the iron carrier Transferrin (TF), reducing reactive oxygen species (ROS), and lipid peroxidation, thereby resulting in resistance to inducers of ferroptosis in melanoma." (PMID 36357379, 2022). "As vascular and tumor cell-derived, TF-bearing EVs were shown to drive coagulopathy, it was shown that TF-expressing EVs promote prothrombotic states in murine models of Lewis lung carcinoma, melanoma, pancreatic cancer." (PMID 36013171, 2022). "Not limited to hepatocytes, transferrin knockdown also impaired tumorigenic capacity of melanoma cells by inducing ferroptosis, while they became more resistant to drug-induced ferroptosis when transferrin was aberrantly overexpressed." (PMID 36211509, 2022). "C TF liposome effects with membrane of cells of different melanoma lines compared with Lip AA5 MIT Vit.C." (PMID 31835393, 2019). "Here, we have prepared transferrin targeted liposomal formulations for co-delivery of mitoxantrone, anacardic acid and ammonium ascorbate to melanoma cells." (PMID 31835393, 2019). "Some of the highly specific biomarkers of melanoma are intracytoplasmic proteins with a low expression on the surface; thus, receptors like transferrin and folic acid that overexpress on the surface of solid tumors like melanoma can be used for targeted drug delivery." (PMID 38022807, 2023). "Immunoblots revealed higher expression levels of transferrin in melanoma cells treated with HPF, indicating that iron uptake could be increased." (PMID 37507910, 2023). "In addition, levels of TF-antigen residues on tumor cells from melanoma patients negatively correlated with tumors’ infiltration by CD8+ T cells, and were linked to a shorter survival." (PMID 36891308, 2023).